ZFAS1 (ZNFX1 antisense RNA 1)
Diseases named in the same sentence as ZFAS1 in open-access papers (continued):
Sharing a sentence is not in itself a finding about the gene and the disease.
diabetic cardiomyopathy (6 papers, 2021 to 2024). Diabetic cardiomyopathy is a disorder of the heart muscle in people with diabetes. "In diabetic cardiomyopathy, ZFAS1 induces ferroptosis by sponging miR-150-5p and activates CCND2 expression." (PMID 39296014, 2024). "Emerging evidence establish the role of lncRNAs in diabetic cardiomyopathy, such as inhibition of lncRNA zinc finger antisense 1 (ZFAS1) prevents cardiomyocyte ferroptosis and improves the progression of diabetic cardiomyopathy using db/db mice." (PMID 39420368, 2024). "Recently, ZFAS1 has been found to regulate ferroptosis in diabetic retinopathy, diabetic cardiomyopathy and pulmonary fibrosis." (PMID 39296014, 2024). "Although there are no previous reports on ZFAS1 alterations in diabetic cardiomyopathy, recent studies have shown that other lncRNAs play an important role in cardiac fibrosis." (PMID 36240130, 2022).
liver cancer (6 papers, 2017 to 2025). An epithelial or non-epithelial malignant neoplasm that arises from the liver. "The lncRNAs of interest for this test—namely ANRIL, H19, HOTAIR, HULC, MALAT1, WISPER, and ZFAS1—were initially identified in other pathologies, as evident in some of their names, highly upregulated in liver cancer (HULC), or metastasis associated lung adenocarcinoma transcript 1 (MALAT1)." (PMID 40271126, 2025). "Mechanistically, ZFAS1 was found to act as a competing endogenous RNA (ceRNA) in liver cancer by binding to miR-150 and inhibiting the tumor suppressor function of miR-150." (PMID 28938617, 2017). "Studies have shown that up-regulation of lncRNA ZFAS1 can promote metastasis in liver cancer." (PMID 34888249, 2021).
thyroid cancer (6 papers, 2020 to 2025). "ZFAS1 overexpression is positively associated with clinicopathological characteristics and poor prognosis in thyroid cancer." (PMID 32760219, 2020). "Recent studies indicate that the long non-coding RNA ZFAS1 functions as an oncogene in thyroid cancer, with expression upregulated in tumor tissues and cell lines." (PMID 41154428, 2025). "Silencing ZFAS1 repressed the invasion ability of TPC-1 cells, suggesting that ZFAS1 was tightly related to thyroid carcinoma metastasis." (PMID 34249125, 2021). "In line with the results found in other cancers, ZFAS1 was also confirmed to show high expression in thyroid carcinoma." (PMID 34249125, 2021). "Collectively, ZFAS1 is positively related to thyroid carcinoma and potentially promotes cancer progression." (PMID 34249125, 2021). "In this study, we validated that lncRNA ZFAS1 promoted thyroid carcinoma cell metastasis by regulating MMP3 via the common miR-373-3p targets." (PMID 34249125, 2021). "In summary, CREB3 activated ZFAS1 drives the metastasis of thyroid carcinoma, which is involved in the miR-373-3p/MMP3 regulatory axis." (PMID 34249125, 2021). "Notably, studies have consistently reported increased expression of ZFAS1 in thyroid cancer (TC) cells, further highlighting its tumor-promoting functions." (PMID 41150811, 2025). "lncRNA ZFAS1 was identified to facilitate thyroid cancer, but its role in medullary thyroid carcinoma (MTC) remains unknown." (PMID 38946718, 2024). "For example, lncRNA FOXD2-AS1 could serve as a novel recurrent marker or a potential target in thyroid cancer and lncRNA ZFAS1 could serve as a novel potential biomarker for predicting the prognosis of thyroid cancer." (PMID 33600548, 2021). "Thus, MMP3 is a promising downstream target of the miR-373-3p/ZFAS1 axis, which is possibly involved in regulating thyroid carcinoma metastasis." (PMID 34249125, 2021). "Therefore, ZFAS1 potentially induced thyroid carcinoma metastasis through regulating the EMT process." (PMID 34249125, 2021). "Both ZFAS1 and MMP3 were highly expressed in thyroid carcinoma and PTC cell, as measured by the q-PCR and TCGA database." (PMID 34249125, 2021). "In thyroid carcinoma, several studies identify that the downregulation of ZFAS1 can inhibit PTC progression through modulating microRNAs (miRNAs), and it can serve as a potential biomarker for predicting thyroid cancer prognosis." (PMID 34249125, 2021). "Using the online prediction tool, CREB3 was predicted as the transcription factor (TF) of ZFAS1 that contained two binding sites on its promoter region, and CREB3 was positively correlated with ZFAS1 in thyroid carcinoma cohorts." (PMID 34249125, 2021). "Knockdown of ZFAS1 led to decreased proliferation, migration, invasion, and EMT in thyroid carcinoma cells, in part by increasing levels of anti-tumor microRNAs such as miR-302a-3p, and subsequently reducing cyclin D1 (CCND1) expression, which promotes cell cycle progression." (PMID 41154428, 2025). "miR-373-3p, ZFAS1, and MMP3 interacted with each other through direct binding, as confirmed by RNA immunoprecipitation; therefore, the ZFAS1/miR-373-3p/MMP3 regulatory axis was critical in thyroid carcinoma metastasis." (PMID 34249125, 2021).
bladder cancer (5 papers, 2018 to 2022). "In conclusion, ZFAS1 overexpression is observed in bladder cancer tissues and cell lines, and associated with aggressive progression in bladder cancer patients." (PMID 29678899, 2018). "The aim of our study is to analyze the association between lncRNA ZFAS1 expression and clinicopathological characteristics in bladder cancer patients, and explored the biological role in regulating bladder cancer cell proliferation, migration, and invasion." (PMID 29678899, 2018). "Then, we observed that the expression level of ZFAS1 was positively associated with clinical stag, muscularis invasion, lymph node metastasis, and distant metastasis in bladder cancer patients." (PMID 29678899, 2018). "However, we observed that the expression level of ZFAS1 was positively associated with clinical stage (P<0.001), muscularis invasion (P<0.001), lymph node metastasis (P<0.001), and distant metastasis (P=0.007) in bladder cancer patients." (PMID 29678899, 2018). "For instance, it was previously proposed that ZFAS1 acts as an oncogene via sponging miR-329 to facilitate bladder cancer tumorigenesis." (PMID 36092160, 2022). "LncRNA ZFAS1 has also been reported to regulate cell proliferation, migration and invasion in bladder cancer by targeting miR-193a-3p/SDC1." (PMID 36240130, 2022). "In order to confirm the prognostic value of ZFAS1 in bladder cancer patients, we still were collecting survival data." (PMID 29678899, 2018). "In order to identify reliable biomarkers for bladder cancer, we analyzed TCGA database, and found ZFAS1 expression was increased in bladder cancer tissues compared with paired adjacent normal tissues (P=0.007)." (PMID 29678899, 2018). "Firstly, we analyzed TCGA database, and found ZFAS1 expression was increased in bladder cancer tissues compared with paired adjacent normal tissues." (PMID 29678899, 2018). "In bladder cancer, ZFAS1 has been shown to be one of the targets for silibinin to regulate cell proliferation, migration, invasion, and apoptosis." (PMID 29678899, 2018). "In conclusion, ZFAS1 is overexpressed in bladder cancer, and functions as an oncogenic lncRNA in regulating bladder cancer cell proliferation, migration, and invasion." (PMID 29678899, 2018). "In order to explore the molecular mechanism of ZFAS1 in bladder cancer, we detected the effect of ZFAS1 on the expression of KLF2, NKD2, and EMT-associated genes (ZEB1, E-Cadherin, and Vimentin) by Western blot." (PMID 29678899, 2018). "According to the expression of ZFAS1 in bladder cancer cell lines (T24, RT4, J82, and SW780), we found that ZFAS1 expression was relatively increased in T24 and RT4 cells." (PMID 29678899, 2018). "In the present study, we found ZFAS1 expression was increased in bladder cancer tissues compared with paired adjacent normal tissues through analyzing the Cancer Genome Atlas (TCGA) database." (PMID 29678899, 2018). "In the early experiment, we explored ZFAS1 expression in bladder cancer tissues through analyzing the Cancer Genome Atlas (TCGA) database, and found ZFAS1 expression was increased in bladder cancer tissues compared with paired adjacent normal tissues." (PMID 29678899, 2018). "The experiments in vitro suggested that knockdown of ZFAS1 repressed bladder cancer cell proliferation via up-regulating KLF2 and NKD2 expression, and inhibited cell migration and invasion via down-regulating ZEB1 and ZEB2 expression." (PMID 29678899, 2018). "Furthermore, we confirmed that levels of ZFAS1 expression were elevated in bladder cancer tissues and cell lines compared with normal bladder tissues and normal uroepithelium cell line, respectively." (PMID 29678899, 2018). "Thus, knockdown of ZFAS1 repressed bladder cancer cell proliferation via up-regulating KLF2 and NKD2 expression, and inhibited cell migration and invasion via down-regulating ZEB1 and ZEB2 expression." (PMID 29678899, 2018).
bladder cancer (continued). "Furthermore, we confirmed the expression of ZFAS1 in 20 pairs of bladder cancer tissue samples and normal bladder tissue samples, and found that levels of ZFAS1 expression were elevated in bladder cancer tissue samples (P<0.001)." (PMID 29678899, 2018). "To further explore the clinical significance of ZFAS1 expression in bladder cancer, we divided all the patients into two groups according to ZFAS1 expression: the ZFAS1 high expression group (n=51) and the ZFAS1 low expression group (n=51) according to a published study." (PMID 29678899, 2018). "Thus, the purpose of the present study is to explore the clinical value of ZFAS1 in bladder cancer patients, and the biological function of ZFAS1 in bladder cancer cell." (PMID 29678899, 2018). "We supposed that ZFAS1 may serve as an oncogenic lncRNA in bladder cancer." (PMID 29678899, 2018). "However, the biological role of ZFAS1 in bladder cancer cell was unknown." (PMID 29678899, 2018). "However, the expression status of ZFAS1 in bladder cancer was still unknown." (PMID 29678899, 2018). "However, the expression status and biological function of ZFAS1 in bladder cancer is still unknown." (PMID 29678899, 2018). "However, the expression status and biological function of ZFAS1 in bladder cancer remain unclear." (PMID 29678899, 2018). "There was no study about the prognostic value of ZFAS1 in bladder cancer." (PMID 29678899, 2018).
breast tumours (5 papers, 2016 to 2019). "ZFAS1 is highly expressed in the mammary gland and is down-regulated in breast tumors compared to normal tissue." (PMID 26928231, 2016). "Besides, lncRNA ZFAS1 has been testified to be down-regulated in the breast tumors compared to normal tissue, and act as tumor biomarker in breast tumour pathology." (PMID 29262629, 2017). "A previous study showed that ZFAS1 is down-regulated in breast tumors compared with normal tissues and the silencing of ZFAS1 in mammary epithelial cell line increased cellular proliferation and differentiation, indicated that ZFAS1 may act as a tumor suppressor gene and the mechanisms were unknown." (PMID 27654478, 2016). "Importantly, ER+ breast tumours had higher expression of ZFAS1 than ER− (negative) breast tumours." (PMID 30288832, 2019).
lung cancer (5 papers, 2017 to 2025). A malignant neoplasm involving the lung. "Methysticin, a naturally occurring inhibitor of NFkB signaling, repressed ZFAS1 while simultaneously upregulating ZNFX1 in a dose-dependent manner in cultured A549 lung cancer cells." (PMID 40211119, 2025). "Given the limited smoking-related lung cancer specimens for analysis of the inverse correlation of ZFAS1 and ZNFX1 and the complexity of cell populations of these specimens, we performed additional correlation analysis using publicly accessible scRNA datasets." (PMID 40211119, 2025). "Overexpression of ZFAS1 enhanced growth of lung cancer cells in vitro and in vivo, suggesting that this lncRNA functions as an oncogene during pulmonary carcinogenesis." (PMID 40211119, 2025). "Furthermore, additional studies are necessary to fully delineate the targets and biological/clinical implications of ZFAS1 activation in tobacco-induced lung cancers." (PMID 40211119, 2025). "In lung cancer, high ZFAS1 expression was significantly related to the poor prognosis." (PMID 28938617, 2017). "Among diverse alterations of lncRNA and coding gene expression profiles in NREC exposed to CSC, we observed upregulation of lncRNA ZFAS1 and repression of an adjacent protein-coding gene, ZNFX1, and confirmed these findings in primary lung cancers." (PMID 40211119, 2025). "Knockdown of SP1 decreased basal expression of ZFAS1, and significantly attenuated CSC-mediated upregulation of this lncRNA in NREC and lung cancer cells." (PMID 40211119, 2025). "Knockdown of NFkB-p65 repressed ZFAS1, and markedly attenuated CSC-induced upregulation of this gene in NREC and lung cancer cells." (PMID 40211119, 2025). "Phenotypic experiments indicated that ZFAS1 is an oncogene, whereas ZNFX1 functions as a tumor suppressor in lung cancer cells." (PMID 40211119, 2025). "qRT-PCR experiments demonstrated that 5-aza-2′ deoxycytidine (DAC);100 nM for 72 h), upregulated ZNFX1 in lung tumor cells while markedly abrogating CSC or ZFAS1 overexpression-mediated ZNFX1 repression in NREC and lung cancer cells." (PMID 40211119, 2025). "Additionally, UV damage‐induced activation of ZFAS1 expression was observed in both IMR‐90 primary human fibroblasts and A549 lung cancer cells." (PMID 40411394, 2025). "Importantly, ZFAS1 is also required in NER in both IMR‐90 primary human fibroblasts and A549 lung cancer cells." (PMID 40411394, 2025). "Immunoblot experiments confirmed that ZFAS1 overexpression decreased ZNFX1 protein levels in SAEC and HBEC; this phenomenon could not be demonstrated in lung cancer cells owing to very low levels of ZNFX1 in control cells (data not shown)." (PMID 40211119, 2025).
non-small cell lung carcinoma (5 papers, 2016 to 2025). A group of at least three distinct histological types of lung cancer, including non-small cell squamous cell carcinoma, adenocarcinoma, and large cell carcinoma. "On the other hand, in non-small cell lung cancer (NSCLC), decreased expression of the lncRNAs MAGI2 antisense RNA 3 (MAGI2-AS3) and ZNFX1 antisense RNA 1 (ZFAS1) was reported in both plasma and platelets." (PMID 39934930, 2025).
pancreatic cancer (5 papers, 2020 to 2025). "In the present report, we found that ZFAS1 is highly expressed in pancreatic cancer, and a high level of ZFAS1 is a risk factor for a poor prognosis in patients with pancreatic cancer." (PMID 34552050, 2021). "Additionally, our Kaplan-Meier survival analysis indicates a noteworthy association between ZFAS1 expression levels and overall poor prognosis and survival rates in ovarian, sarcoma, and pancreatic cancers." (PMID 40109869, 2025). "The lncRNA ZFAS1 plays a carcinogenic regulatory role in many human tumours, but it is rarely reported in pancreatic cancer." (PMID 34552050, 2021). "MS2-RIP, RNA pull-down, RNA-ChIP and luciferase reporter assays were used to clarify the molecular biological mechanisms of ZFAS1 in pancreatic cancer." (PMID 34552050, 2021). "In conclusion, this study revealed a new role for and the molecular mechanisms of ZFAS1 in pancreatic cancer, identifying ZFAS1 as a novel target for the diagnosis and treatment of pancreatic cancer." (PMID 34552050, 2021). "ZFAS1 promoted the growth and metastasis of pancreatic cancer cells, and miR-497-5p acted as a tumour suppressor gene in pancreatic cancer by targeting HMGA2." (PMID 34552050, 2021). "We also found that ZFAS1 promoted the progression of pancreatic cancer in vivo by modulating the miR-497-5p/HMGA2 axis." (PMID 34552050, 2021). "We hope our study will provide new ideas for solving pancreatic cancer problems and translating ZFAS1/miR-3924/ROCK2 signalling knowledge into anticancer therapies." (PMID 32550827, 2020). "ZFAS1 is upregulated in multiple cancers, including gastric, cervical, and pancreatic carcinomas." (PMID 35846429, 2022). "We identify the role and molecular mechanisms of ZFAS1 in pancreatic cancer." (PMID 34552050, 2021). "The expression of ZFAS1, miR-497-5p and HMGA2 in pancreatic cancer tissues was detected by qRT-PCR." (PMID 34552050, 2021). "However, the function and mechanisms of ZFAS1 in pancreatic cancer have not been reported." (PMID 34552050, 2021).
prostate carcinoma (5 papers, 2018 to 2024). A carcinoma that arises from epithelial cells of the prostate gland. "The changes in migratory cellular behavior impled that downregulation of ZFAS1 in prostate cancer might cause a less aggressive phenotype consistent with the clinical data analysis." (PMID 36514044, 2022). "It has been shown that downregulation of the seventh-ranked ZFAS1 reduces the metastasis of prostate cancer cells." (PMID 38431702, 2024). "Specifically, the overexpression of ZFAS1 has been shown to promote the proliferative, invasive, and metastatic ability of prostate cancer cells by regulating miR-135a-5p expression." (PMID 35090549, 2022). "The in vitro analysis further confirmed that down-regulation of ZFAS1 expression decreased prostate cancer cell migration." (PMID 36514044, 2022). "Downregulation of ZFAS1 showed a decreased migratory capacity of prostate cancer cells." (PMID 36514044, 2022). "In-vitro studies confirmed that downregulation of ZFAS1 decreased prostate cancer cell migration." (PMID 36514044, 2022). "Moreover, correlation analysis also revealed miR-940 is positively correlated with GAS5 (PCC=0.47) and ZFAS1 (PCC=0.49) which suggests miR-940 also likely to be involved in prostate cancer." (PMID 29416676, 2018).
colon adenocarcinoma (4 papers, 2018 to 2023). "We report that there is copy number amplification seen with ZFAS1 in the TCGA colon adenocarcinoma cohort." (PMID 33771981, 2021). "Sequencing data downloaded from the The Cancer Genome Atlas (TCGA) database revealed that dysregulated lncRNAs expression in 24 paires of colon adenocarcinoma tissues in comparison with the corresponding ANTs, ZFAS1 was marked with an arrow." (PMID 30250022, 2018).
esophageal cancer (4 papers, 2022 to 2025). A primary or metastatic malignant neoplasm involving the esophagus. "In esophageal cancer, exosomal ZFAS1 is taken up by other surrounding cancer cells and exerts a positive influence on proliferation, migration, and invasion via the miR-124/STAT3 axis." (PMID 35055115, 2022). "Exosomal ZFAS1 may therefore contribute to angiogenesis by affecting the biological traits of nearby endothelial cells in esophageal cancer." (PMID 35055115, 2022).
head and neck squamous cell carcinoma (4 papers, 2015 to 2023). A squamous cell carcinoma that arises from any of the following anatomic sites: lip and oral cavity, nasal cavity, paranasal sinuses, pharynx, larynx, and salivary glands. "ZFAS1 is also upregulated in head and neck squamous cell carcinoma (HNSCC) as it is positively related to cancer initiation and metastasis." (PMID 34249125, 2021).